CYP3A5 (cytochrome P450 family 3 subfamily A member 5)
Diseases named in the same sentence as CYP3A5 in open-access papers (continued):
Sharing a sentence is not in itself a finding about the gene and the disease.
schizophrenia (5 papers, 2024 to 2025). A major psychotic disorder characterized by abnormalities in the perception or expression of reality. "CYP3A5 has been found in the brain, and CYP3A5 genetic variants have previously been associated with schizophrenia, which could support the involvement of the enzyme in the neurobiological process." (PMID 40423221, 2025). "Finally, in one case of schizophrenia, the patient—a CYP3A5*1/1*3 carrier, heavy smoker and regular coffee drinker—did not experience symptom relief until cimetidine was added to the regimen, which led to significant improvement in mental state and behavior." (PMID 40679420, 2025). "Adult patients with schizophrenia will be randomized (2: 1) to receive PGx-assisted treatment (drug and regimen selection depending on the results of single-nucleotide polymorphisms in genes DRD2, HTR1A, HTR2C, ABCB1, CYP2D6, CYP3A5, and CYP1A2) or the standard of care." (PMID 38598465, 2024). "DNA was isolated from the peripheral blood samples of 27 patients with schizophrenia receiving clozapine maintenance treatment, and the pharmacokinetics‐related genes (CYP1A2, CYP2B6, CYP2C19, CYP2D6, CYP3A5, ABCG2, and SLCO1B1) were genotyped." (PMID 40740505, 2025). "Also, GDAs showed that CYP2E1 and CYP3A5 trigger common diseases with CYP2D6 such as ADRs, Drug Allergy, Chemical and drug-induced liver injury, Parkinson’s disease, Schizophrenia, and Mood disorders." (PMID 39505757, 2024). "We investigated the effects of age, sex, and genetic polymorphisms in CYP isoforms (CYP1A2, CYP2B6, CYP2C19, CYP2D6, and CYP3A5) and drug transporters (ABCG2 and SLCO1B1) on the plasma concentrations of clozapine, N‐desmethylclozapine, and clozapine N‐oxide in Japanese patients with schizophrenia." (PMID 40740505, 2025).
acute GVHD (4 papers, 2016 to 2025). "The incidence of acute GVHD and its association with the CYP3A5 genotype has only been explored in the studies by Khaled and Yamashita, which also identified CYP3A5*1/*1 as an independent risk factor for acute GVHD." (PMID 38794124, 2024). "Multivariate analysis confirmed CYP3A5 intermediate and extensive metabolizers as an independent risk factor for acute GVHD (HR 3.5 [95% CI 1.5–8.3], p = 0.003) as well as clinically relevant acute GVHD (grades II-IV) (HR 4.5 [95% CI 2.4–8.6], p < 0.001)." (PMID 38794124, 2024). "In this study, the relationship between acute GVHD and CYP3A5 polymorphism within four weeks after HSCT was investigated." (PMID 31096684, 2019). "We observed that the cumulative incidence of grade 2–4 acute GVHD tended to be higher in individuals with the CYP3A5*1 allele than in those with CYP3A5*3/*3." (PMID 31096684, 2019). "There was a significant difference in the cumulative incidence of grade III–IV severe acute GVHD between the patients with the CYP3A5*1 allele and the CYP3A5*3/*3 allele (36 vs. 0 %, P = 0.017)." (PMID 27217047, 2016). "Here, we investigated the influence of genotypes of CYP3A5, CYP2C19, and POR on the concentration/dose (C/D) ratio of tacrolimus and episodes of acute graft-versus-host disease (GVHD) in Japanese recipients of allogeneic hematopoietic stem cell transplantation (HSCT)." (PMID 31096684, 2019). "CYP3A5 genotyping may be useful for determination of the appropriate dose of Tac-QD and the selection of AZ, in order to avoid AKI as well as severe acute GVHD." (PMID 27217047, 2016).
chronic kidney disease (4 papers, 2021 to 2025). Impairment of the renal function secondary to chronic kidney damage persisting for three or more months. "A single-nucleotide polymorphism, CYP3A5*3 (rs776746), produces a non-functional variant that may influence progression of chronic kidney disease (CKD) by impairing renal filtration." (PMID 40330700, 2025).
colorectal cancer (4 papers, 2007 to 2023). A primary or metastatic malignant neoplasm that affects the colon or rectum. "The allele frequencies for CYP3A5*3 were 91.9 (95% CI 89.0–94.7), 95.7 (95% CI 92.6–98.8), and 91.7% (95% CI 88.6–94.8) for liver, stomach and colorectal cancer patients, respectively, and 90.8% (95% CI 87.7–93.9) among healthy individuals." (PMID 17605821, 2007). "However the interaction of CYP3A4 and CYP3A5 gene polymorphisms and the risk of developing the major digestive cancers such as liver, stomach or colorectal cancers remain unexplored." (PMID 17605821, 2007). "Studies have shown that CYP3A5 plays an important role in the development of acute and chronic leukemia, colorectal cancer, and esophageal cancer." (PMID 32350633, 2020). "CYP3A4 and CYP3A5 genotypes were determined in 574 individuals including 178 patients with primary liver cancer, 82 patients with gastric cancer, 151 patients with colorectal cancer, and 163 healthy individuals." (PMID 17605821, 2007). "Both CYP3A4 and CYP3A5 are expressed in liver, stomach, colorectal epithelium and in colorectal cancer tissue, although large interindividual differences exist in the expression of both enzymes." (PMID 17605821, 2007). "Recent evidence, however, suggests that tumor cell-intrinsic expression of CYP3A5 may underpin intrinsic drug resistance in colorectal cancer and PDAC37,42." (PMID 37679568, 2023). "CYP3A4 and CYP3A5 genotypes in colorectal cancer patients according tumor site." (PMID 17605821, 2007).
epilepsy (4 papers, 2010 to 2025). A brain disorder characterized by episodes of abnormally increased neuronal discharge resulting in transient episodes of sensory or motor neurological dysfunction, or psychic dysfunction. "Analyzing the distribution of CYP3A5 alleles in the groups of patients with epilepsy, as well as in control group, we found statistically significant more frequent occurrences of homozygotes of CYP3A5*3/*3 than heterozygotes of CYP3A5*1/*3." (PMID 23984379, 2013). "Additionally, the authors attempted to assess the cooccurrence of allele variants of gene CYP3A5 allele *1/*3 or *3/*3 and the CC, CT, or CT genotypes with resistance to drugs in epilepsy." (PMID 23984379, 2013). "The isoenzyme CYP3A5 is functionally and quantitatively related to CYP3A4, which has been connected with the expression of glycoprotein P and the resistance to AEDs; thus, it seems that also the polymorphism of CYP3A5 may have its share in the drug resistance mechanisms in epilepsy." (PMID 23984379, 2013). "The results indicate the influence of genotype of CYP3A5 upon the distribution of CBZ in patients with epilepsy." (PMID 23984379, 2013). "The influence of CYP2C19 and CYP3A5 genotypes on the population clearance estimates of zonisamide were assessed in 99 Japanese patients with epilepsy." (PMID 27713373, 2010). "Our analyses failed to confirm the connection between polymorphism of CYP3A5 with drug resistance in epilepsy." (PMID 23984379, 2013). "Many genetic polymorphisms play a role in the pathogenesis and treatment of epilepsy, e.g., SCN1A ABCG2, SCN1A, CYP3A5, and SCN2A." (PMID 39920787, 2025). "The study did not confirm the association between CYP3A5*3 polymorphism and C3435T polymorphism in the MDR1 gene and pharmacological epilepsy." (PMID 34769124, 2021). "In contrast to CYP2C19, the CYP3A5*3 genotype did not affect the clearance of zonisamide, indicating that CYP3A5*3 genotypes do not have a major impact on the zonisamide pharmacokinetics in Japanese patients with epilepsy." (PMID 27713373, 2010). "Conversely, the CYP3A5*3 genotype did not affect the clearance of zonisamide, indicating that the CYP3A5*3 genotypes do not contribute significantly to the zonisamide pharmacokinetics in Japanese patients with epilepsy." (PMID 27713373, 2010).
hepatocellular carcinoma (4 papers, 2020 to 2025). A malignant tumor that arises from hepatocytes. "By regulating mTORC2/Akt Signaling, CYP3A5 serves as a tumor suppressor in hepatocellular carcinoma." (PMID 36983670, 2023). "Similarly, Tingdong suggests that the lower the expression of CYP3A5, the worse the prognosis in hepatocellular carcinoma patients." (PMID 32350633, 2020). "CYP3A5, which is downregulated in hepatocellular carcinomas, has been found to suppress HCC pathogenesis by inducing ROS accumulation and subsequent inhibition of mTORC2/Akt signaling." (PMID 39754188, 2025). "Several genes of the cytochrome P450 family were upregulated in treated cells compared to controls, including the CYP3A5 gene, a tumor suppressor in hepatocellular carcinoma (HCC) that plays an important protective role in HCC metastasis." (PMID 38928215, 2024).
Hypercholesterolemia (4 papers, 2021 to 2023). An increased concentration of cholesterol in the blood. "The present study showed associations between CYP3A4*22 (rs35599367) and CYP3A5*3 (rs776746) SNP combination genotypes with response to statins in hypercholesterolemia." (PMID 35839255, 2022). "This study aimed to investigate the association of CYP3A4*22 (rs35599367), CYP3A5*3 (rs776746) single nucleotide polymorphism (SNP) with response to simvastatin in hypercholesterolemia patients conducted at King Abdulaziz University hospital (KAUH) in Jeddah, Saudi Arabia." (PMID 35839255, 2022). "A study reported the genotype frequency of the CYP3A5 genetic variations in 350 unrelated Greek Caucasian cases with primary hypercholesterolemia: 13.4% for expressors and 86.6% for non-expressors (homozygous) subjects." (PMID 37759317, 2023).
neuropathy (4 papers, 2016 to 2025). A disorder affecting the nervous system that manifests with pain, tingling, numbness, and/or muscle weakness. "Thus, the CYP3A5*3 genotype causes increased vincristine exposure, leading to higher neuropathy incidence and severity grade; however, information on clinical impact was not reported." (PMID 31214762, 2019). "In contrast, molecular markers, including polymorphisms in the hepatic vincristine metabolizer CYP3A5, displayed great promise in predicting increased incidence and severity of neuropathy; however, further studies are warranted to assess its use in treatment prediction." (PMID 31214762, 2019). "Because of clinical signs of neuropathy (hand-tremor) and severely reduced CYP3A5-activity (homozygous *3/*3 genotype), Vincristine-treatment was terminated." (PMID 40581649, 2025). "Consistently, antifungal drugs, such as itraconazole and voriconazole, inhibit the action of CYP3A5; consequently, coadministration of vincristine and these drugs decreases vincristine metabolism, leading to enhanced neuropathy side effects." (PMID 31214762, 2019). "At our hospital, we also observed severe neuropathy in CYP3A5 poor metabolizers independent of CEP72 and ABCB1 status." (PMID 27618021, 2016).
pancreatic cancer (4 papers, 2022 to 2024). "In summary, these findings prove that CYP3A5 regulates glucose uptake in pancreatic cancer cells." (PMID 38560501, 2024). "CYP3A5 contributes to cell migration by maintaining high glucose uptake in pancreatic cancer." (PMID 38560501, 2024).
Thrombocytopenia (4 papers, 2018 to 2024). A reduction in the number of circulating thrombocytes. "Increased CYP3A5 genetic variants were associated with increased thrombocytopenia (a cytotoxic side effect of PTX), suggesting that CYP3A5 must be functional for PTX metabolism to occur." (PMID 33182737, 2020). "The increased catalytic activity of this G allele variant and also CYP3A5 has been suggested to increase conversion of sunitinib to its metabolite, SU12662; excessive accumulation of SU12662 has been associated with grade 3 thrombocytopenia and leukopenia." (PMID 29788981, 2018). "Furthermore, the liver enzymes CYP3A4 and CYP3A5 are also trapped in the drug metabolism of T-DM1, and patients with mutations in these two genes are susceptible to AEs associated with T-DM1, especially thrombocytopenia." (PMID 38741766, 2024). "For the CYP3A5 genotype (GG/GG), controlling the blood concentration of tacrolimus below the target concentration until POD3 can avoid thrombocytopenia-related complications." (PMID 38002088, 2023).
chronic myeloid leukemia (3 papers, 2012 to 2024). "This study aimed to explore the influence of SLC22A1, PXR, ABCG2, ABCB1 and CYP3A5*3 genetic polymorphisms on imatinib mesylate (IM) pharmacokinetics in Asian patients with chronic myeloid leukemia (CML)." (PMID 23272163, 2012). "Notably, the CYP3A5*3 SNP has been associated with the likelihood of developing chronic myeloid leukemia (CML)." (PMID 39523378, 2024). "CYP3A5*3 and ABCB1 C3435T variants influence clinical outcomes and plasma concentrations of Imatinib in Nigerian patients with chronic myeloid leukaemia." (PMID 32858798, 2020).
esophageal cancer (3 papers, 2011 to 2020). A primary or metastatic malignant neoplasm involving the esophagus. "CYP3A5 is the major P450 enzyme in the esophagus, and polymorphisms in CYP3A5 have been proposed as risk factors for esophageal cancer, which is highly prevalent among African males in South Africa." (PMID 22563365, 2011). "Some genes like GSTP1 was related with ESCC in the South African population; high CYP3A5 activity could increase esophageal cancer risk in Black Africans." (PMID 28410201, 2017).
liver cancer (3 papers, 2007 to 2020). An epithelial or non-epithelial malignant neoplasm that arises from the liver. "Liver cancer, CYP3A5*3 polymorphism, and miR-142 were independent factors for the variability of CYP3A5 mRNA with the model R2 = 0.35." (PMID 27211076, 2016). "Low CYP3A5 expression was correlated with aggressive vascular invasion, poor differentiation, and poor survival in liver cancer." (PMID 33202946, 2020). "For example, CYP3A5 has been reported as a tumour suppressor that inhibits liver cancer cell migration and invasion through suppressing ROS/mTORC2/p-AKT kinase signaling." (PMID 33202946, 2020).
Myalgia (3 papers, 2016 to 2023). "It showed that the CYP3A5*3 variant was allied to the increase in the serum level of creatine kinase (CK) in the case of individuals with myalgia." (PMID 37759317, 2023). "Caucasians with myalgia while using atorvastatin were at significant risk of suffering severe muscle damage if they were carriers of CYP3A5*3/*3." (PMID 37759317, 2023). "The study concluded that individuals with myalgia while using atorvastatin were at a high risk of developing a severe myopathy if they were carriers of the CYP3A5*3/*3 genotype (P<0.05)." (PMID 37759317, 2023). "CYP3A5 *3/*3 subjects were related to higher risk of myalgia and muscle damage compared to *1/*3 subjects and to increased response to atorvastatin compared to *1/*1 + *1/*3 subjects." (PMID 33805706, 2021). "Patients who develop myalgia while taking AT are more likely to experience a greater degree of muscle damage if they express two copies of CYP3A5*325." (PMID 27211076, 2016).
Obesity (3 papers, 2020 to 2026). Accumulation of substantial excess body fat. "We found the gene CYP3A5 is reported as one of loci associated with obesity related traits in GWAS studies." (PMID 32027667, 2020). "Notably, CYP3A5 and CTSA formed two separate networks with connectivity 6 and 3 respectively to obesity related gene." (PMID 32027667, 2020). "An analysis of 4βOHC concentrations based on genotype did not indicate elevated 4βOHC in the individuals expressing CYP3A5 *1/*3 compared with CYP3A5 *3/*3 expressors, neither in normal to overweight individuals (p = 0.95) nor in patients with obesity (p = 0.33)." (PMID 35648149, 2022).
acute kidney injury (2 papers, 2013 to 2016). Sudden and sustained deterioration of the kidney function characterized by decreased glomerular filtration rate, increased serum creatinine or oliguria. "The cumulative incidence of acute kidney injury was higher in patients with the CYP3A5*3/*3 than with the CYP3A5*1 allele when AZ was co-administered." (PMID 27217047, 2016). "One of the three patients expressing functional CYP3A5 experienced renal failure during the study period." (PMID 23566530, 2013).
acute liver failure (2 papers, 2018). Rapid deterioration of liver function causing encephalopathy and coagulopathy. "DNA samples obtained from patients enrolled by the Acute Liver Failure Study Group suggest the rs776746 polymorphism in CYP3A5 is associated with increased bioactivation of paracetamol via increased enzyme activity." (PMID 29067481, 2018). "Recently, it has been suggested that polymorphisms in the CD44 (rs1467558) and CYP3A5 (rs776746) genes might contribute to risk for paracetamol-induced acute liver failure, in addition to the previously discovered UGT1A-39UTR variant (rs8330)." (PMID 30274302, 2018).
acute lymphoblastic leukaemia (2 papers, 2008 to 2021). "Indeed, low CYP3A5 expression has been associated with an increased risk of VIPN in children with acute lymphoblastic leukemia." (PMID 34080039, 2021).
adenoma (2 papers, 2005 to 2020). A neoplasm arising from the epithelium. "Protein level of CYP3A5 was ~54% lower in biopsies obtained from patients with adenoma when compared to disease-free controls." (PMID 16281975, 2005). "At the level of mRNA expression, only the expression of CYP3A5 was found to be significantly altered between neoplastic tissue and normal, unaffected mucosa of patients with adenoma." (PMID 16281975, 2005). "Expression of CYP2C, CYP2E1, CYP3A4, and CYP3A5 in colon mucosa of normal and adenomatous colonic tissue of patients with adenoma and disease-free controls was determined by RT-PCR." (PMID 16281975, 2005). "Similar results were found when comparing protein levels of CYP3A4 and CYP3A5 between patients with adenoma and disease-free controls." (PMID 16281975, 2005). "At the level of protein, CYP2C8, CYP3A4, and CYP3A5 protein concentration was found to be significantly lower in normal tissue of patients with adenoma than in colon mucosa of disease-free controls." (PMID 16281975, 2005). "CYP3A5 mRNA expression was significantly higher in adenoma in comparison to normal tissue of patients with adenoma (~48%)." (PMID 16281975, 2005). "When comparing the relative mRNA concentration of CYP2C, CP2E1, CYP3A4, and CYP3A5 between adenomatous tissue and normal tissue of patients with adenoma, significant differences were only found for the expression of CYP3A5." (PMID 16281975, 2005). "Taken together, these data suggest that CYP expression not only varies extensively between individuals but that protein levels of some CYPs (e.g. CP2C8, CYP3A4, and CYP3A5) are considerably lower in normal tissue of patients with adenoma in comparison to those of disease-free controls." (PMID 16281975, 2005). "CYP3A5 is induced by corticosteroids in the liver and can both induce drug resistance and activate prodrugs; it is the subject of ongoing studies in several neoplasias and could represent a viable drug target for corticotrope adenomas from female patients." (PMID 32183012, 2020). "In contrast, in normal tissue of patients with adenomas protein levels of CYP3A4 and CYP3A5 were contrary to mRNA expression pattern." (PMID 16281975, 2005). "With the exception of CYP3A5, expression of CYP mRNA was similar among groups and tissues (e.g. normal colon mucosa and adenoma)." (PMID 16281975, 2005). "Interestingly, CYP3A5 together with CALB1, DAPL1 and FZD9 were recently reported to be enriched in human ACTH-secreting adenomas compared to other pituitary adenomas." (PMID 32183012, 2020). "However, in normal tissue of patients with adenomas, protein levels of CYP2C8, CYP3A4 and CYP3A5, but not that of CYP2E1, were significantly lower than in biopsies obtained from disease-free controls." (PMID 16281975, 2005).